RN7SL563P (RNA, 7SL, cytoplasmic 563, pseudogene)
Gene: Miscellaneous RNA gene on chromosome 8 (101,397,636 to 101,397,933, reverse strand). Ensembl gene ENSG00000239211.
Homologues: Orthologues: chimpanzee Metazoa_SRP (98% identical), macaque Metazoa_SRP (92% identical). Paralogues in human: RN7SL1 (82% identical), RN7SL2 (81% identical), RN7SL3 (80% identical), RN7SL650P (80% identical), RN7SL709P (79% identical), RN7SL126P (78% identical), RN7SL717P (78% identical), RN7SL408P (78% identical), RN7SL577P (78% identical), RN7SL589P (78% identical), RN7SL797P (78% identical), RN7SL230P (77% identical), and 704 more.